RNU6-552P (RNA, U6 small nuclear 552, pseudogene)
Gene: Small nuclear RNA gene on chromosome 14 (45,274,359 to 45,274,477, reverse strand). Ensembl gene ENSG00000199739.
Homologues: Orthologues: chimpanzee U6 (99% identical), macaque U6 (83% identical), mouse Gm25793 (82% identical), pig U6 (80% identical), guinea pig U6 (71% identical), dog U6 (69% identical), guinea pig U6 (60% identical). Paralogues in human: RNU6-21P (80% identical), RNU6-333P (80% identical), RNU6-854P (80% identical), RNU6-144P (79% identical), RNU6-20P (79% identical), RNU6-211P (79% identical), RNU6-73P (79% identical), RNU6-820P (79% identical), RNU6-936P (79% identical), RNU6-1013P (78% identical), RNU6-1029P (78% identical), RNU6-1152P (78% identical), and 1283 more.